APOB (apolipoprotein B)
Diseases named in the same sentence as APOB in open-access papers (continued):
Sharing a sentence is not in itself a finding about the gene and the disease.
diabetes (continued). "When adjusted for sex, age, BMI, hypertension, diabetes, hyperuricemia, TG, TC, WBC, HGB, alcohol use, and smoke status, ApoB at baseline remained significantly correlated with the CKD occurrence (HR, 1.76; 95% CI: 1.00-3.07) (P = 0.048)." (PMID 37124758, 2023). "On univariable analysis, age, duration of diabetes, GE index, hypertension, dyslipidaemia, METS-IR, apoB, apoA, apoB/A, ALT, TBIL, Hb, SII, PP, DR, and ASCVD were significantly associated with DKD (P<0.01 or P<0.05)." (PMID 38239983, 2023). "After adjusting for age, sex, BMI, hypertension, diabetes, hyperuricemia, TG, TC, WBC, HGB, alcohol use, and smoke status, the baseline ApoB increase was still correlated with the occurrence of CKD (HR, 1.61; 95% CI: 1.02-2.54) (P = 0.042)." (PMID 37124758, 2023). "After adjusting for sex, age, BMI, hypertension, diabetes, hyperuricemia, TG, TC, WBC, HGB, alcohol use, and smoke status, serum ApoB level was still significantly positively correlated with CKD prevalence." (PMID 37124758, 2023). "Other characteristics including BMI, hypertension, diabetes mellitus, TG, TC, HDL-C, LDL-C, apolipoprotein AI, and apolipoprotein B were comparable between the patient group and the control group." (PMID 37215191, 2023). "Participants with higher ornithine concentrations tended to be male and had higher BMI, Glu, Cr, UA, apoB, and Hcy levels, lower PLT, HDL-C, and apoA levels, and a higher prevalence of hypertension, diabetes, coronary artery disease, smoking, and drinking." (PMID 37492403, 2023). "Also, triglyceride, serum ApoB, and serum ApoA1 levels did not improve, which is of interest, because all 3 of these parameters are mentioned as risk factors for developing posttransplant diabetes mellitus." (PMID 36593877, 2022). "In addition, our results demonstrated that BMI and diabetes were positively correlated with the increased levels of ApoB and LDL, respectively, which may be due to the fact that AnxA6 stimulates endocytosis and is involved in the trafficking of LDL to the pre-lysosomal compartment." (PMID 36498634, 2022). "Patients with elevated hs-CRP were older, had a higher prevalence of hypertension, diabetes, and cigarette smoking and STEMI, and higher levels of TC, LDL-C, apoA, apoB, FPG, HbA1c and NT-proBNP." (PMID 35282356, 2022). "In summary, the novel findings from our study are that discordantly high levels of ApoB in relation to LDL-C are related to an increased likelihood of prevalent CKD, even in the presence of inflammation, diabetes, hypertension, and a range of other predictors." (PMID 35054008, 2022). "The correlation between HCV eradication and blood levels of ApoB, ApoE, and VLDL should be analyzed in future studies, as these are important subclasses of lipids in the context of diabetes." (PMID 36140194, 2022). "GCG, IRS1, VEGFA, STAT3, CCL2, CASP3, and APOE as diabetes mellitus-related proteins and SREBF1, LPL, PPARA, APOB, GPT, MAPK8, and FASN as NAFLD-specific proteins were identified as possible discriminating factors between the two studied diseases." (PMID 35154608, 2021). "Particularly, LVEF, diabetes history, and serum LDL-C, ApoB, glucose, and Pcsk9 levels were significantly different between these subgroups (all P < 0.05)." (PMID 34044829, 2021). "Proportions of diabetes history, serum LDL-C, ApoB, glucose and Pcsk9 levels were highest in the SS > 21.5 group, while the proportion of LVEF was lowest in the SS > 21.5 group." (PMID 34044829, 2021). "Among patients with T2DM who had a reduced eGFR, those with NADKD had a shorter duration of diabetes and a lower level of SBP, DBP, PP, TC, ApoB, ApoB/ApoAI, and prevalence of anemia than patients with AGDKD." (PMID 34022855, 2021). "We first included the following variables in the model: age, sex, education level, smoking and drinking history, diabetes duration, insulin use, BMI, HbA1c, FBG, PBG, HDL-C, LDL-C, TC, TG, ApoA1, ApoB, sLPR1, and the LRP1 genotype." (PMID 33013281, 2020).
diabetes (continued). "Previous studies have shown that diabetes is a risk factor for SCM, and hyperlipidemia is a risk factor for diabetes, so it can be speculated that hyperlipidemia is a potential risk factor for SCM, so compared with the normal population, APOE and APOB genes are upregulated in SCM patients." (PMID 32695227, 2020). "Smoking, diabetes, hypertension, manual work, and fewer than nine years of education were more common, while body mass index, TC, TG, LDL, apoB, and the ratio apoB/apoA-1 and glucose levels were higher, among CV cases than controls." (PMID 30138379, 2018). "The prevalence of pre-diabetes and T2DM in women were increased in sequence from the bottom to the top tertiles of the ApoB/ApoA-I ratio (for pre-diabetes: T1:16.5%, T2:19.8%, T3:25.5%, p=0.014; for diabetes, T1:6.2%, T2:22.2%, T3:32.1%, p<0.001)." (PMID 28110289, 2017). "The ApoB/ApoA-I ratios were significantly increased across the spectrum of NGT, pre-diabetes and T2DM." (PMID 28110289, 2017). "The diabetes patients had higher diastolic blood pressure, HbA1c, total cholesterol, LDL cholesterol, apoB, apoA-I, body weight, body mass index (BMI) and waist circumference compared with controls both at baseline and at the 5-year follow-up." (PMID 28683835, 2017). "Mean values of triglycerides, total cholesterol, ApoB and the ApoB/ApoA-I ratio increased and mean values of HDL-C and ApoA-I successively decreased from subjects with normal glucose levels to those with pre-diabetes and newly diagnosed type 2 diabetes." (PMID 25353659, 2014). "There were significant correlations between IMT and; apoB, CRP and systolic blood pressure (SBP) and there were significant correlations between PWV and; diabetes duration, SBP, BMI, WC and SAD." (PMID 23536999, 2013). "Our study showed, however, that adiponectin, apoB, CRP, and ferritin improved the prediction of diabetes consistently in two independent cohorts even after taking BMI, blood glucose and other classic risk factors into account." (PMID 20396381, 2010). "This was corroborated on a genetic level where patients without diabetes, but not diabetics, in the alternative LPA GRS variant group had higher plasma ApoB compared with those in the reference group." (PMID 41164877, 2026). "Patients without diabetes, but not diabetics, with high plasma Lp(a) had significantly higher levels of plasma ApoB." (PMID 41164877, 2026). "ApoB or non-HDL-C assessment is recommended for individuals with persistent residual risk, such as those with diabetes or persistent hypertriglyceridemia." (PMID 41010649, 2025). "The current findings align with a large observational study of 13,523 Korean males, which demonstrated a significant association between serum apoB and CAD risk in individuals without diabetes or hypertension." (PMID 40852379, 2025). "T1DM: type 1 diabetes mellitus; T2DM: type 2 diabetes mellitus; PCSK9: proprotein convertase subtilisin/kexin type 9; LDL-C: low-density lipoprotein-cholesterol; HDL-C: high-density lipoprotein-cholesterol; Apo-B: apolipoprotein B." (PMID 40264627, 2025). "In the fully adjusted model, which included age, gender, smoking, hypertension, diabetes, CKD, ApoA1, ApoB, albumin, uric acid, eGFR, fibrinogen, LVEF, and Gensini score, Lp(a) remained linearly and positively associated with all-cause and cardiovascular mortality (P-nonlinear = 0.528 and 0.859)." (PMID 40496568, 2025). "The measurement of ApoB and ApoA1 does not require fasting samples and is standardized, making the ApoB/ApoA1 ratio a more balanced, comprehensive, and stable indicator of lipid metabolism and a predictor of cardiovascular disease and diabetes." (PMID 40463506, 2025). "Furthermore, APOB/APOA1 can be used for the prediction of CAVD, and the combination of APOB/APOA1 with age, history of diabetes, DBP, Cys-c, and NLR has better prediction performance for CAVD." (PMID 40787622, 2025).
diabetes (continued). "Adults aged ≥ 20 years without diagnosed diabetes and with complete data on their ApoB and glycemic markers were included." (PMID 40423035, 2025). "Conversely in subjects with low-apoB, LDL/ATP-induced WAT IL-1β-secretion was associated in the direction of lower diabetes risk, associating positively with IS and negatively with WAT expression of ADGRE1 and MCP1." (PMID 39511203, 2024). "rs7257062 was foundto be an independent risk factor of CAD (OR = 1.581, 95% CI: 1.094–2.284,p = 0.015) in a multivariable logistic analysis, after controlling forpotential confounders including gender, smoking history, diabetes, hypertension,TG, TC, HDL-C, LDL-C and ApoB." (PMID 39076552, 2024). "The concentration of glycated apoB is also raised when LDL is increased even in the absence of diabetes, for example in familial hypercholesterolaemia." (PMID 36873390, 2023). "The associations between baseline ApoB levels and the occurrence of CKD were analyzed in individuals with or without hypertension, diabetes, hyperuricemia, and hypohemia." (PMID 37124758, 2023). "Clinical trials should test if substantial remnant cholesterol-lowering therapy without increases in LDL-cholesterol and apolipoprotein B can prevent ASCVD in diabetes." (PMID 37776347, 2023). "In the patient group, S1PR5 was correlated with diabetes, heart rate, triglycerides (TG), total cholesterol (TC), low-density lipoprotein cholesterol (LDL-C), apolipoprotein B (ApoB), and fasting blood glucose (P < 0.05); CARNS1 was correlated with uric acid (UA) (P < 0.05)." (PMID 35837598, 2022). "Carriers of rs12740374 with diabetes had a greater decrease in plasma apoB, TG, VLDL, and LDL compared with people without diabetes." (PMID 35113816, 2022). "After adjusting for age, body mass index, sex, hypertension, diabetes, smoking, TC, LDL-C, ApoA, and ApoB, S1PR5 was correlated with CHD (odds ratio 2.164, 95% CI: 1.670–2.804, P < 0.05), suggesting that higher S1PR5 expression may increase the risk of CHD." (PMID 35837598, 2022). "Diabetes, TG, TC, LDL-C, ApoB, and UA are CHD-related metabolism indicators, suggesting S1PR5 and CARNS1 may be related to the pathogenesis of CHD." (PMID 35837598, 2022). "APOE genotypes affect IHD risk increasingly from ε2ε3, ε3ε3, ε3ε4 to ε4ε4, with similar patterns for pulse pressure and plasma apoB, but not for diabetes." (PMID 33927215, 2021). "Our findings suggested that total cholesterol, triglyceride, ApoB, and ApoE were significantly correlated with the degree of LFC in MAFLD patients with obesity or diabetes, while stepwise increase in LDL-c and FFA was only associated with higher LFC in those with obesity/overweight." (PMID 34899591, 2021). "A review article which was looking for a relationship between diabetes and FHBL found that the latter condition resulting from APOB gene variants does not seem to cause an increase in the risk of diabetes mellitus (DM)." (PMID 34564380, 2021). "In the same study, the median serum apolipoprotein B-100 level was significantly higher in diabetes with cardiovascular complications than without complications." (PMID 32867226, 2020). "MoCA score was considered the dependent variable, and age, sex, education level, diabetes duration, insulin use, BMI, HbA1c, FBG, PBG, TC, TG, LDL-C, HDL-C, ApoA1, ApoB, and sLRP1 were considered the independent variables in the multiple linear regression analysis." (PMID 33013281, 2020). "In our study, we also find an increased ratio of apoB: apoA1 value was a highly significant risk factor of CAD independent of smoking, hypertension, and diabetes." (PMID 30134981, 2018). "The sdLDL-C levels were significantly higher in the hyper-TG/-apoB group independent of subjects’ characteristics, and these levels were significantly higher in patients with diabetes or CAD than those in healthy subjects." (PMID 28125987, 2017).
diabetes (continued). "We show here that 4 months metformin administration initiated directly after the acute phase of MI is associated with slight reductions reduced LDL cholesterol without affecting apoB levels in a large group of patients without previously established diabetes." (PMID 26808474, 2016). "LDL-C, non-HDL-C and ApoB levels are inter-correlated and all predict risk of atherosclerotic cardiovascular disease (ASCVD) in patients with type 2 diabetes mellitus (T2DM) and/or high TG." (PMID 27405296, 2016). "Cardiovascular risk factors used for the study included metabolic risk factors (waist circumference, TG, HDL-C, fasting blood glucose, systolic and diastolic blood pressures), diabetes-related factors (insulin, HbA1c, HOMA-IR), and heart disease-related factors (AI, hsCRP, homocysteine, ApoB)." (PMID 26497880, 2015). "An apoB level <90 mg/dL was proposed in patients without diabetes or known CVD but with ≥2 additional major CVD risk factors, or with diabetes and without major CVD risk factors." (PMID 21356116, 2011). "However, large case series and meta‐analyses have not supported a significant increase in diabetes among individuals with FHBL1, concluding that genetically low LDL‐C due to APOB truncating variants is not inherently diabetogenic." (PMID 41549954, 2026). "However, despite the reduced statistical power, the study was able to demonstrate an association of Lp(a) with cardiovascular mortality (independent of ApoB and other covariates including diabetes), highlighting the extent of this effect." (PMID 41164877, 2026). "The fasting blood glucose (GLU), total cholesterol(TC), triglyceride (TG), low-density lipoprotein cholesterol(LDL-C), non-high-density lipoprotein cholesterol (nonHDL-C), apolipoprotein A-1 (ApoA-1), and apolipoproteinB (ApoB) levels, as well as diabetes rates, were lower (P=0.01)." (PMID 41821770, 2026). "Univariate logistic regression analysis incorporating hypertension, diabetes, lipid profiles, apolipoprotein levels, and liver function parameters demonstrated statistically significant differences (p < 0.05) between severe and mild groups for diabetes, hypertension, LDL, ApoA, and ApoB." (PMID 40822937, 2025). "The use of antidiabetic drugs and diabetes mellitus were predictors of LDL-C levels, contributing 2.7% and 1.6% of the total variance, respectively, whereas the use of antidiabetic drug was a predictor of ApoB levels in males, contributing 2.4% of the total variance." (PMID 39080710, 2024). "Additionally, ApoB/ApoA-I was significantly correlated with stroke recurrence in the no-diabetes and LAA subgroups." (PMID 38274879, 2023). "While LDL-C, non-HDL-C, and apoB concentrations are highly correlated, there are clinical scenarios (e.g., in patients with diabetes) where LDL-C might underestimate the concentration of atherogenic apoB-containing lipoproteins." (PMID 37620933, 2023). "However, the hazard ratios of ApoB/ApoA-I were not significant in the subgroups of female individuals, history of diabetes, and non-LAA stroke." (PMID 38274879, 2023). "After controlling for age, gender, body mass index, duration of hypertension and type 2 diabetes mellitus, apoB/non-high density lipoprotein cholesterol (HDL-C) (p=0.015) was an independent risk factor for nAMD, apoB was an independent risk factor for PCV(p=0.011), compared with control." (PMID 35928899, 2022). "While plasma apoB measurements were not available, we were able to replicate the observed decrease in plasma TG in rs12740374 carriers with diabetes as compared with people without diabetes in our internal Penn Medicine Biobank (data not shown)." (PMID 35113816, 2022).
diabetes (continued). "Compared with patients having high levels of ApoB (≥65 mg/dL), patients with low ApoB (<65 mg/dL) had higher prevalence of elderly patients (18.96 vs. 13.75%), hypertension (59.25 vs. 55.76), CKD (23.22 vs. 21.47%), diabetes mellitus (29.25 vs. 26.51%) and anemia (40.90 vs. 30.11%)." (PMID 35146010, 2022). "Ultimately, sex and age; duration of diabetes; BMI; hypertension; previous use of antihypertensive drugs, RASIs, and lipid-lowering drugs; smoking; PP; duration of hypertension; and FPG, HbA1c, TG, TC, HDL-C, LDL-C, and ApoB/ApoAI levels were considered as independent variables." (PMID 34022855, 2021). "In addition, apolipoprotein A1 increased (with the exception of patients with diabetes receiving placebo-etanercept) and adiponectin increased slightly through week 24; leptin and apolipoprotein B did not change." (PMID 27704313, 2016). "Recently, a consensus panel convened by the American Diabetes Association and the American College of Cardiology recommended a greater focus on non-HDL cholesterol and apoB levels in patients who are likely to have small LDL particles, such as diabetic patients." (PMID 23284722, 2012). "Hence, for CKD patients without diabetes, ApoB levels may offer more informative guidance for those at risk of DN." (PMID 40379620, 2025). "Opposite associations were observed for total LDL cholesterol and concentrations of LDL particles, ApoB, remnant cholesterol, phospholipids, cholesteryl esters in LDL particles, and omega‐3 FAs, which appeared positively associated with liver fat among those without diabetes only." (PMID 36872307, 2023). "However, there was evidence of effect modification by diabetes status for all four IgM OSE, with significant interaction tests (IgM MDA-LDL P interaction = 0.001, IgM MDA-P1 mimotope P interaction =0.026, IgM PC-BSA P interaction = 0.022, IgM apoB-IC P interaction = 0.002." (PMID 37211249, 2023). "Among participants with diagnosed diabetes, undiagnosed diabetes, prediabetes, and normoglycemia, significant decreases occurred in concentrations of total cholesterol, low-density lipoprotein cholesterol, non-high-density lipoprotein cholesterol, and apolipoprotein B." (PMID 23360385, 2013). "So, In this study, plasma levels of apoA1 and apoB were compared in diabetic children with type I diabetes mellitus (DM), healthy children with nondiabetic parents (HNDPs), and healthy children with diabetic parents (HDPs)." (PMID 22811893, 2012). "In a routine clinical setting, usually dealing with individual risk estimation or risk stratification between dozens to hundreds of patients, both non-HDL-C and apoB performed equally well to discriminate between diabetic patients, and may be considered as interchangeable surrogates in diabetes." (PMID 21356116, 2011). "This discordance is significant in statin users with low LDL-C but elevated ApoB or non-HDL-C and also in individuals with diabetes, obesity, hypertriglyceridemia, or metabolic syndrome—where classic LDL-C underestimates risk." (PMID 41010649, 2025). "However, under specific circumstances [e.g., for patients with very-low LDL-C levels, diabetes mellitus (DM), a high concentration of triglycerides (TG), obesity], assessments based on LDL-C might underestimate the ASCVD risk, and non-HDL-C or direct apoB measurements are superior." (PMID 39200791, 2024). "Patients in the severe CAD group were older and had higher rates of diabetes, as well as increased levels of serum CR, UA, TC, LDL-C, ApoB, non-HDL-C, CRI I, CRI II, TG/HDL-C, AI, AIP, LCI was higher than mild CAD group." (PMID 37441702, 2023). "There were significant differences in the gender, waist circumference, BMI, diabetes, FG, triglyceride, HDL-C, LDL-C, total cholesterol, apolipoprotein B and PANSS score between obesity and no obesity patients (all p < 0.05)." (PMID 35690794, 2022).